RALGPS1 (Ral GEF with PH domain and SH3 binding motif 1)
Description:
Guanine nucleotide exchange factor (GEF) for the small GTPase RALA. May be involved in cytoskeletal organization (By similarity). Guanine nucleotide exchange factor for.
Synonyms: KIAA0351; RALGEF2; RALGPS1A
Tractability: Antibody: UniProt places it where antibodies can reach, with high confidence; its Gene Ontology location is reachable by antibodies, with medium confidence. PROTAC: ubiquitination databases record sites on it; its protein half-life has been measured.
Gene: Protein-coding gene on chromosome 9 (126,914,774 to 127,223,166, forward strand). Ensembl gene ENSG00000136828.
Subcellular location: Cytoplasm; Cell membrane
Gene Ontology:
Molecular function: guanyl-nucleotide exchange factor activity
Biological process: regulation of Ral protein signal transduction; intracellular signal transduction; small GTPase-mediated signal transduction
Cellular component: plasma membrane; cytoplasm
Genetic constraint (gnomAD): Loss-of-function variants: 17 observed, 71.14 expected, observed/expected ratio (o/e) 0.24, 90% interval 0.16 to 0.36. The upper end of that interval is the gene's LOEUF score, 0.36, which puts it in group 1 of 6, group 1 being the genes least tolerant of losing a copy. Missense variants: 430 observed, 656.22 expected, observed/expected ratio (o/e) 0.66, 90% interval 0.61 to 0.71. Synonymous variants: 208 observed, 246.39 expected, observed/expected ratio (o/e) 0.84, 90% interval 0.75 to 0.95.
Homologues: Orthologues: chimpanzee RALGPS1 (100% identical), macaque RALGPS1 (100% identical), rabbit RALGPS1 (97% identical), dog RALGPS1 (97% identical), guinea pig RALGPS1 (97% identical), mouse Ralgps1 (97% identical), rat Ralgps1 (96% identical), pig RALGPS1 (85% identical), tropical clawed frog ralgps1 (85% identical), zebrafish ralgps1 (76% identical). Paralogues in human: RALGPS2 (64% identical), RASGRP3 (22% identical), RAPGEF2 (20% identical), RASGRP2 (20% identical), RASGRP1 (19% identical), RAPGEF6 (19% identical), RGL1 (19% identical), RALGDS (18% identical), RGL3 (18% identical), SOS1 (18% identical), RASGRP4 (18% identical), SOS2 (18% identical), and 12 more.
Diseases named in the same sentence as RALGPS1 in open-access papers:
RALGPS1 is named in the same sentence as 14 diseases in open-access papers, as found by Europe PMC text mining. Sharing a sentence is not in itself a finding about the gene and the disease. The quoted sentences say what the papers report.
encephalitis (1 paper, 2025). An acute inflammatory process affecting the brain parenchyma. "TAF1 and DPM2 provide potential clues about parkinsonism and increased creatine phosphokinase in neuroleptic malignant syndrome, while abnormalities in RALGPS1 suggest links to both anti-NMDAR antibody encephalitis and the SHANK3 gene, which is known to predispose to catatonia." (PMID 40400398, 2025).
lymph node metastasis (1 paper, 2022). "A similar well-designed study aimed at identifying the genes associated with the involvement of lymph node metastasis in patients with PCa and, among 376 genes investigated, three genes, RALGPS1, ZBTB34 and GOLGA1, had a significant copy number alteration." (PMID 36077746, 2022).
ovarian teratoma (1 paper, 2021). A non-seminomatous germ cell tumor arising from the ovary. "RALGPS1 dysfunction might include abnormalities of biogenesis of GPI dependent on the DPM complex and, with any decrease in THY-1, might yield possible clues in pathophysiology of ovarian teratomas." (PMID 34745385, 2021).
cancer (2 papers, 2021). A tumor composed of atypical neoplastic, often pleomorphic cells that invade other tissues. "RALGPS1, NUDT9, NUDT2, and PDE4A were less expressed in cancer cell lines; JUP, ADA, HPRT1, and IMPDH1 were highly expressed in cancer cell lines in CCLE." (PMID 34745385, 2021).
tumor (2 papers, 2018 to 2021). "Therefore, suppression of RALGPS1 may cause mitochondrial fission failure so as to inhibit tumor invasion, chemotaxis, and metastasis." (PMID 34745385, 2021).
RALGPS1 also shares sentences with these, for which no sentence is quoted: autism (1 paper); bipolar disorder (1); breast carcinoma (1); epilepsy (1); lung carcinoma (1); major depressive disorder (1); neuroleptic malignant syndrome (1); Parkinsonism (1); schizophrenia (1).